PIEZO1 (piezo type mechanosensitive ion channel component 1 (Er blood group))
Diseases named in the same sentence as PIEZO1 in open-access papers (continued):
Sharing a sentence is not in itself a finding about the gene and the disease.
cancer (continued). "Specifically, in the OS analysis, cancers such as LGG and ACC continued to exhibit significant prognostic associations following age adjustment, further supporting the potential value of PIEZO1 as an independent prognostic biomarker." (PMID 40977743, 2025). "In recent studies, the Cell@CaP vaccine, through specific activation of the Piezo1 channel, has effectively enhanced DC function and demonstrated promising potential in the design of personalized cancer vaccines." (PMID 41195420, 2025). "Recent studies have reported that Piezo1 is involved in regulating the functions of various immune cells, including macrophages, DCs and T cells, in infectious inflammation and cancer." (PMID 39890818, 2025). "The cell surface receptor integrin is a mechanosignal transducer that can be activated by Piezo1 to promote cancer stem cells and drug resistance." (PMID 40061015, 2025). "Here we show that microconstriction activates signal transduction cascades through PIEZO1, priming cells to adopt an invasive cancer stem cell-like state, that is poised to engage with the endothelium, extravasate and colonise distal tissue sites." (PMID 40890143, 2025). "Collectively, our results establish PIEZO1’s oncogenic role and therapeutic potential across cancers." (PMID 40977743, 2025). "On metabolic and immunological fronts, Piezo1-triggered ATP release can shift cancer cells toward a dual-activated state characterized by high oxidative phosphorylation (OXPHOS) and glycolysis." (PMID 40821847, 2025). "Our work establishes mechano-metabolic coupling as a core regulator of CAR T cell fitness and pinpoints Piezo1 tuning as a new strategy to enhance cancer immunotherapy." (PMID 41282104, 2025). "Our findings indicate that PIEZO1 is a promising marker for the diagnosis, prognosis, and development of targeted pan-cancer therapies." (PMID 40977743, 2025). "Despite these insights, a comprehensive pan-cancer analysis of PIEZO1’s role in various cancers is still needed." (PMID 40977743, 2025). "Piezo-type mechanosensitive channel component 1 (PIEZO1), a mechanically gated cation channel involved in calcium signaling, has been recognized as a potential oncogene in some cancers." (PMID 40977743, 2025). "The increase of ECM stiffness significantly upregulates Piezo1 expression at both cell and tissue levels, and high Piezo1 expression indicates a poor prognosis in cancer patients." (PMID 39801760, 2025). "In conclusion, this work prevents a safe, noninvasive, and highly translatable mechanotherapy to treat cancer, which is based on the synergistic activation of Piezo1." (PMID 39976192, 2025). "From a clinical standpoint, PIEZO1 appears to be a dynamic ion channel protein, affecting varying cancers differently." (PMID 38398074, 2024). "In the ultrasonic-targeted microbubble therapy of pancreatic ductal cell carcinoma, Piezo1 blockade reduced Ca2+ influx, decreased cytochrome C and Bax, and increased Bcl-2, which finally assisted microbubble to induce apoptosis of cancer cells." (PMID 38690080, 2024). "Other gene sets related to cancer aggressiveness, including hypoxia, apical junction, angiogenesis, and glycolysis, were also enriched in high-PIEZO1 HR-negative tumors." (PMID 38398074, 2024). "PIEZO1 is a mechanosensitive ion channel protein that promotes cancer progression and MDSC expansion." (PMID 38786019, 2024). "In other words, the expression of Piezo1 steered macrophages toward the pro-inflammatory M1 polarization state and away from the anti-inflammatory and pro-cancer M2 polarization state." (PMID 38690080, 2024). "Piezo1 has also been described as affecting the immune response by enhancing myeloid-derived suppressor cells in cancer and infectious diseases, inhibiting immune responses, and, thus, promoting cancer proliferation." (PMID 39001475, 2024).
cancer (continued). "PIEZO1’s effect on small GTPases has been shown to affect migration in both neural crest cells and cancer cells, Cadherin remodeling in lymphatic endothelial cells, and macrophage mechanotransduction in iron metabolism." (PMID 38578817, 2024). "Piezo1 regulates cancer cell migration and invasion by modulating cell adhesion, stiffness, and contractility, thus influencing invadopodia formation and MMP expression." (PMID 38390363, 2024). "Intriguingly, recent work similarly identified Piezo1 as a regulator of epidermal growth factor-stimulated macropinocytosis in cancer cells." (PMID 38265917, 2024). "We anticipate the development of promising drugs or peptides for cancer therapy targeting the Piezo1/integrin β1 axis." (PMID 39258781, 2024). "The reduced Piezo1 expression in metastatic SW630 cells suggests that the potential downregulation of Piezo1 is a survival mechanism for cancer cells during the transitional phase." (PMID 38544822, 2024). "In summary, arginine‐rich peptides play a crucial role in enhancing the delivery efficiency to cancer by facilitating the escape of contents from endosomes, a process mediated by Piezo1/integrin β1 axis." (PMID 39258781, 2024). "In fact, there are numerous intersecting roles of GPCs and PIEZO1 in tissue development and in cancer." (PMID 39356664, 2024). "The activation of Piezo1 ion channel exacerbated heat-induced injury of 4T1 cells, and this property was appropriate for the application of hyperthermia therapy in cancer." (PMID 38463518, 2024). "To validate our bioinformatic results, we are conducting further experimental studies to identify the mechanistic role of PIEZO1 and confirm the involvement of PIEZO1 in highlighted pro-cancer pathways and T cell infiltration." (PMID 38398074, 2024). "It has also been shown that Piezo1 plays a crucial role in the development of cancer metastases on multiple levels of this process." (PMID 36837670, 2023). "In this cancer, Piezo1 enhances cell proliferation and motility and, therefore, cancer migration and invasion." (PMID 36837670, 2023). "A similar synergistic effect was observed in patient‐derived organoid models, pointing to an increased sensitivity of cancer cells to 5‐FU following PIEZO1 depletion." (PMID 37983931, 2023). "It has been shown that Piezo1 signaling in inflammatory cells promotes cancer progression and myeloid-derived suppressor cells (MDSCs) expansion." (PMID 36837670, 2023). "Research has revealed that the activation of PIEZO1 elevates mitochondrial membrane potential (Ψm) and intracellular Ca2+ levels in GC cells, with Ψm serving a pivotal role in cancer metastasis and angiogenesis." (PMID 37983931, 2023). "In summary, our findings suggest that H. pylori infection accelerates early‐stage GC progression by upregulating NFKB1/RELA transcription mediated by PIEZO1 in cancer cells." (PMID 37983931, 2023). "Since Piezo1 was discovered and characterized, it has been described as playing a role in a myriad of cancers." (PMID 37762011, 2023). "This function appears to be relevant to cancer surveillance, as deletion of Piezo1 in myeloid cells reduced pancreatic cancer progression." (PMID 37781915, 2023). "For instance, it has been observed that genetic ablation of Piezo1 in dendritic cells inhibits the generation of Th1 cells and drives the development of Treg cells, promoting cancer growth in mice." (PMID 37762011, 2023). "The Piezo1 expression level was significantly increased in cancer compared to pre-cancerous tissues." (PMID 36837670, 2023). "As mechanosensors, Piezo1/2 perceive external mechanical cues to influence the proliferation, migration, apoptosis, and invasion of cancer cells." (PMID 37864030, 2023). "This suggests that endothelin signaling controlled by Piezo1 plays a role in cancer paracrine communication and metabolism." (PMID 36837670, 2023).
cancer (continued). "It was shown that downregulation of Piezo1 expression inhibits the proliferation and migration of cancer cells in vitro as well as the growth of tumors implanted into mice." (PMID 36837670, 2023). "Piezo1 plays a role in promoting angiogenesis, which allows the escape of cancer cells through leaky vasculature." (PMID 36837670, 2023). "Matrix stiffness induced by Piezo1 promotes N-cadherin expression on endothelial cells, which supports a mesenchymal phenotype in cancer cells, allowing them to squeeze between cells during intravasation." (PMID 36837670, 2023). "Pivoting to the functional aspects of PIEZO1 as a mechanosensor in the microenvironment of GC, we sought to explore how PIEZO1 mediates downstream signaling in cancer cells." (PMID 37983931, 2023). "Further, mechanical stretch has been demonstrated to kill cancer cells but promote normal cell growth in vitro via mechano-sensitive Piezo1-mediated calcium signaling." (PMID 37864030, 2023). "One possibility is that the increased mechanical forces cancer cells experience as they invade and migrate will activate the Piezo1-SFK-p38-EGFR axis, thereby promoting cell proliferation and chemo-resistance." (PMID 37756411, 2023). "When it comes to metastasis capability, Piezo1 induces migration of confined cancer cells but inhibits that of unconfined ones." (PMID 36837670, 2023). "To corroborate the oncogenic function of PIEZO1, we carried out functional tests that illustrated that depleting PIEZO1 hindered patient‐derived organoid growth, curtailed monolayer colony formation of cancer cells, and compromised GC cell invasion." (PMID 37983931, 2023). "Piezo1’s contribution to cancer cell invasion is also ensured by calcium signal initiation, actin protrusion formation (invadopodia), and enhanced matrix degradation." (PMID 36837670, 2023). "Mechanistically, Piezo1 promotes cancer cell metastasis and invasion by promoting cell migration, elevating the production of angiogenic factors, and enhancing matrix remodeling." (PMID 37781915, 2023). "We further assessed the potential correlations between PIEZO1 expression levels and genetic alteration, protein phosphorylation, immune infiltration and pathway enrichment in 33 types of cancers." (PMID 35747124, 2022). "Curiously, based on the cancer type, Piezo1 was either found to be upregulated (in breast, gastric, prostate, and bladder cancers) or downregulated (as observed for lung cancer)." (PMID 35897650, 2022). "We examined PIEZO1 across thirty-three types of cancers to explore its role in prognosis and immunological function for the first time." (PMID 35747124, 2022). "Based on the open databases TCGA, GTEx and CPTAC, PIEZO1 has been demonstrated to be differentially expressed in most cancers compared to adjacent normal tissues." (PMID 35747124, 2022). "Cancer cells can be stimulated by the calcium-ion channels of Piezo1, by converting mechanical stimuli into electrochemical signals." (PMID 36615408, 2022). "Genetic deletion of Piezo1 in DCs inhibited the generation of TH1 cells while driving the development of Treg cells in promoting cancer growth in mice." (PMID 35993548, 2022). "Taken together, our observations indicated that Piezo1 was critical in malignant tumors events, including invasion and metastasis." (PMID 36112948, 2022). "We further explore the possible molecular mechanisms of Piezo1 in OC by focusing on the Hippo/YAP pathway, which has been shown to be associated with abnormal tissue growth and tumorigenesis of multiple cancers, including OC." (PMID 35942515, 2022). "The importance of PIEZO1 activity in immune cells has been confirmed which implies the potential contribution of PIEZO1 to cancer immunotherapies." (PMID 35747124, 2022). "It is however worth noting that the role of Piezo1 in cancer progression appears to be tissue-dependent." (PMID 35942515, 2022).
cancer (continued). "Some recent findings highlight the possibility of considering Piezo1 as a valid biomarker, as well as a potential target for cancer therapies." (PMID 35897650, 2022). "The confirmed role of PIEZO1 activity in immune cells raises the possibilities of utilizing PIEZO1 for cancer immunotherapies." (PMID 35747124, 2022). "Then, we conducted the Cignal Finder Cancer 10-Pathway Reporter Array (Qiagen, Germany) in Piezo1 expression interfered HCC cells to further screen and confirm the signaling pathway regulated by Piezo1." (PMID 35461277, 2022). "A growing body of evidence indicates that the expression and function of Piezo1/2 are altered in cancer." (PMID 36158191, 2022). "PIEZO1, a mechanosensitive ion channel protein, has been identified in the correlation between several cancers." (PMID 35747124, 2022). "The mechanosensor Piezo1 not only mediates the effects of ECM stiffness on cancer cells, but also contributes to ECM rigidity-induced expansion of immunosuppressive myeloid cells." (PMID 35331296, 2022). "Recently, our study and work by others have reported that Piezo1 from all kinds of immune cells is involved in regulating many diseases, including infectious inflammation and cancer." (PMID 36615408, 2022). "On the other hand, ECM stiffening can activate the mechanosensor Piezo1, which is a mediator of mechanical force-induced cancer metastasis." (PMID 35331296, 2022). "Piezo1 is also a vital regulator of innate immune responses and targeting Piezo1 in myeloid cells is protective against cancer with a reduced infiltrate of immune cells." (PMID 35461277, 2022). "In this study, we examine the role that lipid rafts and the raft-stabilizing polyphenol resveratrol (RSV) have on the mechanical and chemical activation of Piezo1 in order to sensitize cancer cells to therapeutics." (PMID 36080197, 2022). "Metastatic SW620 cells exhibited decreased Piezo1 expression, suggestive of Piezo1 downregulation for the survival of cancer cells in transit." (PMID 36080197, 2022). "Piezo1 and/or Piezo2 are overexpressed in several cancers of epithelial origin, where these channels act as oncogenes, enhancing carcinogenesis through different Ca2+-dependent signalling pathways." (PMID 35806388, 2022). "Piezo1 exerts significant regulatory effects on many kinds of immune cell functions including macrophages, DCs, and T cells in inflammation and cancer." (PMID 35993548, 2022). "Global inhibition of Piezo1 with a peptide inhibitor showed protective effects against both cancer and septic shock." (PMID 35993548, 2022). "In this review, we investigate the research progress of Piezo1 in the immunomodulatory mechanism, and Piezo1 has profound effects on inflammation and cancer." (PMID 36615408, 2022). "To further confirm the specificity of Piezo1 in mediating compression-enhanced cancer cell invasion, we examined the expression of Piezo1 in MDA-MB-231 cells." (PMID 34979904, 2022). "The interconnection between some of these cancers and Piezo1 activity opened a new research field for future targeted therapies against this protein." (PMID 35897650, 2022). "In line with this, Piezo1 knockdown inhibits the adhesion capacity of these cancer cells, thereby preventing cell metastasis." (PMID 35942515, 2022). "For instance, we have recently determined that cancer cells can be sensitized to tumor necrosis factor-related apoptosis inducing ligand (TRAIL)-mediated apoptosis through the activation of Piezo1, either through FSS or chemical agonists such as Yoda1." (PMID 36080197, 2022). "The different effects of Piezo1 in promoting metastasis in different types of cancers indicate the complex diversity in the progression of the cancer." (PMID 36615408, 2022). "In the development and progression of cancer of the gastric duct, Piezo1 regulates epithelial homeostasis, promoting the proliferation, migration, and invasion of cancer cells." (PMID 36615408, 2022).
cancer (continued). "Another possibility is that FSS naturally selects for subpopulations of cancer cells that are impervious to the stress of shear due to lower innate levels of Piezo1." (PMID 36080197, 2022). "Calpains activated by Piezo1 increase cancer cell motility through reorganization of actin and remodeling of the cytoskeleton." (PMID 34831037, 2021). "Motility is also enhanced through the mechanosensitive response of Piezo1 to confinement, which is upregulated in cancers." (PMID 34831037, 2021). "The diverse responses of Piezo1 in inducing cell death, increasing cell survival, modulating immune cell activation, and enhancing cancer metastasis demonstrates the complexity of cancer progression." (PMID 34831037, 2021). "Recent research showed that the Piezo1 channel is closely correlated with some types of cancers, including oral squamous cell carcinoma, prostate cancer and colon cancer." (PMID 33422128, 2021). "In this review, we discuss the roles of Piezo1 in each stage of cancer metastasis in addition to its roles in immune cell activation and cancer cell death." (PMID 34831037, 2021). "Cancer cells and other cells can transduce physical stimuli into biochemical responses using the mechanosensitive ion channel Piezo1, which is activated by membrane deformations that occur when cells are exposed to physical forces." (PMID 34831037, 2021). "The roles of Piezo1 in both survival and apoptosis further demonstrate the diverse roles of Piezo1 in cancer metastasis." (PMID 34831037, 2021). "Piezo1 is a mechanosensitive ion channel (MSC) that has recently been associated with multiple steps in the metastatic cascade (for a review on Piezo1 in different cancer types see De Felice and Alaimo)." (PMID 34831037, 2021). "Although Piezo1 is not specifically mentioned, the impact of Ca2+ influx, an important result of Piezo1 opening, has been observed in cancer cell extravasation." (PMID 34831037, 2021). "Downregulation of Piezo1 that considerably suppressed Ca2+ signal increments, inhibits the phosphorylation of Akt in human prostate malignant tumour tissues, preventing Akt activation." (PMID 33994356, 2021). "The demonstrated importance of Piezo1 activity in immune cells gives rise to the potential of using Piezo1 to modulate cancer immunotherapies and infectious disease treatment." (PMID 34831037, 2021). "PIEZO1 is an intrinsically mechanosensitive ion channel that can interact with many signalling pathways in multiple cancer malignancies." (PMID 32999349, 2020). "Currently, two primary limitations preclude the pharmacological and genetic targeting of Piezo1 in the treatment of cancer." (PMID 32635333, 2020). "Different types of cancer are characterized by an increased expression of both Piezo1 and Piezo2 whilst, in a few, they are downregulated, proof of their direct implication in these pathologies." (PMID 32635333, 2020). "In these cells, knocking down channel expression decreased the Ca2+ response to the agonist Yoda1 and cell migration, suggesting Piezo1 as a plausible cancer cell regulator." (PMID 32635333, 2020). "Overall, the potential drug targeting of Piezo1 in cancer therapy is still challenging and needs to be more thoroughly investigated." (PMID 32635333, 2020). "Microarray Piezo1 expression of the four cancer cell lines was gathered from the CBioportal to correlate its effects on Yoda1-TRAIL sensitization." (PMID 31685811, 2019). "This implies that Piezo1 activation sensitizes cancer cells to TRAIL through a calcium influx that activates calpains." (PMID 31685811, 2019). "The role of Piezo1 and Piezo2 channels in the development of inflammatory, cancer and/or neuropathic pain conditions remains to be explored in detail." (PMID 29497363, 2018). "Because PIEZO1 is highly expressed in MCF-7 cells and is substantially inhibited by GsMTx-4, it is proposed that PIEZO1 is a potential regulator of cancer cell motility." (PMID 29757938, 2018).